RELB (RELB proto-oncogene, NF-kB subunit)
Description:
NF-kappa-B is a pleiotropic transcription factor which is present in almost all cell types and is involved in many biological processed such as inflammation, immunity, differentiation, cell growth, tumorigenesis and apoptosis. NF-kappa-B is a homo- or heterodimeric complex formed by the Rel-like domain-containing proteins RELA/p65, RELB, NFKB1/p105, NFKB1/p50, REL and NFKB2/p52. The dimers bind at kappa-B sites in the DNA of their target genes and the individual dimers have distinct preferences for different kappa-B sites that they can bind with distinguishable affinity and specificity. Different dimer combinations act as transcriptional activators or repressors, respectively. NF-kappa-B is controlled by various mechanisms of post-translational modification and subcellular compartmentalization as well as by interactions with other cofactors or corepressors. NF-kappa-B complexes are held in the cytoplasm in an inactive state complexed with members of the NF-kappa-B inhibitor (I-kappa-B) family. In a conventional activation pathway, I-kappa-B is phosphorylated by I-kappa-B kinases (IKKs) in response to different activators, subsequently degraded thus liberating the active NF-kappa-B complex which translocates to the nucleus. NF-kappa-B heterodimeric RelB-p50 and RelB-p52 complexes are transcriptional activators. RELB neither associates with DNA nor with RELA/p65 or REL. Stimulates promoter activity in the presence of NFKB2/p49. As a member of the NUPR1/RELB/IER3 survival pathway, may provide pancreatic ductal adenocarcinoma with remarkable resistance to cell stress, such as starvation or gemcitabine treatment. Regulates the circadian clock by repressing the transcriptional activator activity of the CLOCK-BMAL1 heterodimer in a CRY1/CRY2 independent manner. Increased repression of the heterodimer is seen in the presence of NFKB2/p52. Is required for both T and B lymphocyte maturation and function.
Synonyms: REL-B; I-REL; IMD53; IREL
Tractability: PROTAC: ubiquitination databases record sites on it; its protein half-life has been measured.
Target class: Transcription factor
Gene: Protein-coding gene on chromosome 19 (45,001,461 to 45,038,192, forward strand). Ensembl gene ENSG00000104856.
Subcellular location: Nucleus; Cytoplasm, cytoskeleton, microtubule organizing center, centrosome
Subcellular location (Human Protein Atlas): Nucleoplasm; Cytosol
Pathways (Reactome):
Immune System: CD209 (DC-SIGN) signaling; Dectin-1 mediated noncanonical NF-kB signaling; NIK-->noncanonical NF-kB signaling
Gene Ontology:
Molecular function: protein binding; protein kinase binding; RNA polymerase II cis-regulatory region sequence-specific DNA binding; DNA-binding transcription factor activity, RNA polymerase II-specific; DNA binding; DNA-binding transcription factor activity; identical protein binding
Biological process: lymphocyte differentiation; negative regulation of interferon-beta production; canonical NF-kappaB signal transduction; circadian regulation of gene expression; inflammatory response; innate immune response; non-canonical NF-kappaB signal transduction; positive regulation of transcription by RNA polymerase II; response to cytokine; cellular response to osmotic stress; negative regulation of DNA-templated transcription; regulation of DNA-templated transcription; regulation of gene expression
Cellular component: centrosome; chromatin; nucleoplasm; nucleus; protein-containing complex; transcription repressor complex; cytosol; NF-kappaB complex; cytoplasm; synapse
Genetic constraint (gnomAD): Loss-of-function variants: 14 observed, 42.76 expected, observed/expected ratio (o/e) 0.33, 90% interval 0.22 to 0.51. The synonymous counts are far from expectation, so gnomAD's model fits this gene poorly and the ratio says little. Missense variants: 661 observed, 729.23 expected, observed/expected ratio (o/e) 0.91, 90% interval 0.85 to 0.97. Synonymous variants: 407 observed, 329.17 expected, observed/expected ratio (o/e) 1.24, 90% interval 1.14 to 1.34.
Gene-disease validity (ClinGen):
ClinGen rates the evidence that RELB causes each of these diseases.
immunodeficiency 53 (autosomal recessive): Definitive.
Homologues: Orthologues: macaque RELB (97% identical), dog RELB (93% identical), pig RELB (93% identical), chimpanzee RELB (92% identical), mouse Relb (87% identical), rat Relb (86% identical), guinea pig RELB (84% identical), tropical clawed frog relb (42% identical), zebrafish relb (36% identical), Drosophila melanogaster dl (29% identical), Drosophila melanogaster Dif (26% identical). Paralogues in human: RELA (31% identical), NFKB2 (28% identical), REL (27% identical), NFKB1 (27% identical).
Diseases named in the same sentence as RELB in open-access papers:
RELB is named in the same sentence as 175 diseases in open-access papers, as found by Europe PMC text mining. Sharing a sentence is not in itself a finding about the gene and the disease. The quoted sentences say what the papers report.
breast carcinoma (48 papers, 2005 to 2025). "The expression of EZH2 is linked to the expression of RelB, which is differentially expressed between ER-negative and ER-positive breast cancer lines." (PMID 39768352, 2024). "IKKα expression was associated mainly with ER-positive tumors, whereas IKBKβ, p50, and p65 from the canonical, and NIK, p52 and RELB from the alternative NF-κB pathway were associated with better RFS of breast cancer patients." (PMID 31602271, 2019). "In support of a potential clinical relevance, we also found that low PAK4/high RELB expression was associated with better prognosis in the HER2-positive breast cancer subtype, in which PAK4 expression was the highest." (PMID 31399573, 2019). "On the other hand, we observed that expression of IKBKβ, p50, and p65 from the canonical, and NIK, p52 and RELB from the alternative NF-κB pathway were associated with better RFS of breast cancer patients." (PMID 31602271, 2019). "NIK is reported to be associated with activation of NF-κB in basal-like breast cancer and IKKα, RelB and p52 are associated with decreased cancer-specific survival in ER-positive breast disease." (PMID 30347849, 2018). "Furthermore, RelB has been implicated in cancer progression, particularly in sex hormone-related cancers, including PCa, breast cancer and endometrial cancer." (PMID 35177112, 2022). "Moreover, RelB activation is inversely associated with ERα-positive breast cancer patients and is indicative of unfavourable survival odds." (PMID 29983639, 2018). "The results indicated that high expression levels of OPN4, NOS2, GPR157, NCOA2, CLOCK, and TH were associated with shorter OS in breast cancer patients, while high expression of EGR3, NR1H3, RELB, SIAH2, and ADRB1 was linked to improved survival rates." (PMID 41031266, 2025). "For example, RelB-mediated GPX4 upregulation facilitates tamoxifen resistance in breast cancer, while GPX4 inactivation induces ferroptosis and augments chemotherapy sensitivity." (PMID 39935430, 2025). "ER-positive breast cancer cell lines in which RelB expression is repressed, have PRC2 form a complex with the ER and collectively negatively regulate NF-κB by repressing NF-κB target promoters." (PMID 39768352, 2024). "For example, the activation of TNF-α upregulated ESM1 expression by the RelB subunit of NF-κB in breast cancer cells." (PMID 39309430, 2024). "As a result, NF-κB inducing kinase (NIK) increased at the protein level and promoted the nuclear localization of NF-κB2 (p52) and RelB in the highly malignant breast cancer cell line." (PMID 37005661, 2023). "TCDD also induced dimerization of AhR and RelB of the alternative NF-κB pathway and up-regulation of CXCL8 through a novel RelB/AhR response element (RelBAHRE) in macrophages and breast cancer cells." (PMID 37696458, 2023). "According to the Human Protein Altas database, RelB was considered as an independent factor in breast cancer and renal cancer prognosis." (PMID 37388242, 2023). "Several RELB target genes that were positively regulated or suppressed in breast cancer cells showed a tendency to be up- and down-regulated, respectively, in A–T versus control cerebellar microglia." (PMID 35212385, 2022). "Silencing of RelA and RelB decreases the organotropic ability of exosomes in vivo and significantly reduces their ability to promote breast cancer migration and invasion." (PMID 35765040, 2022). "This inverse correlation was also observed at the protein level in Hs 578T breast cancer cells where PAK4 knockdown upregulated RELB." (PMID 31399573, 2019). "Here, the authors show that PAK4 overrides this senescence in breast cancer cells through phosphorylation of RELB, thereby inhibiting transcription of the senescence regulator C/EBPβ." (PMID 31399573, 2019).
breast carcinoma (continued). "RelB expression in breast cancer cells promotes an epithelial-to-mesenchymal transition (EMT), and supports the self-renewal of tumor initiating cells." (PMID 29874793, 2018). "RelB in turn has been shown to inhibit estrogen receptor expression in breast cancer cells by upregulating a transcriptional repressor Blimp1." (PMID 29874793, 2018). "On the other hand, there is an inverse correlation of ERα expression and NF-κB sub-unit RelB expression in breast cancer cell lines and human breast cancer samples." (PMID 26797644, 2016). "NF-kB Rel proteins with a trans-activating domain negatively regulate proliferation, albeit in specific cell types: RelA in murine fibroblasts, pro-B cells and breast cancer cells, RelB in murine fibroblasts and cRel in HELA cells." (PMID 26460486, 2015). "The viral protein IE1 mediates the binding of NF-κB complexes to the RELB promoter, resulting in RelB synthesis, which then induces Bcl-2, leading to more invasive breast cancer cells." (PMID 25699089, 2014). "Since mRNA levels of the NFkB subunit RELB are elevated in basal-type breast cancer cells, NFkB signals in those cells can also be blocked with shRNA targeting the RELB gene." (PMID 24243820, 2013). "Recently we observed aberrant Blimp1 expression in breast cancer cells resulting from an NF-κB RelB to Ras signaling pathway." (PMID 22438909, 2012). "In breast cancer, RelB-mediated GPX4 upregulations drive tamoxifen resistance." (PMID 39935430, 2025). "RelB/AhR complex is also involved in the overexpression of CXCL8 in breast cancer." (PMID 36588678, 2022). "NIK and RELB were mainly expressed by the basal breast cancer cell line MDA-MB-231." (PMID 31602271, 2019). "In addition, we show that the low PAK4/high RELB pattern of expression correlates with better prognosis in HER2-positive breast cancer patients." (PMID 31399573, 2019). "Furthermore, the AhR has been shown to bind to NF-κB subunit RelB and that interaction of RelB and AhR in the breast cancer cell lines MCF-7 and MDA-MB-436 induced IL-8 expression." (PMID 29487603, 2018). "Bennett reported that IKKα expression and not NIK or RelB is associated with recurrence in Luminal A breast cancer, suggesting it is independent of the non-canonical NF-κB pathway." (PMID 30347849, 2018). "Similarly, high nuclear levels of active RelB were found in carcinogen-induced murine mammary tumors and nuclear RelB was found to be significantly elevated in nuclei from ER- inflammatory breast cancer tissue samples." (PMID 27764181, 2016). "In addition, inhibition of RelB in human breast cancer cells reduced cyclin D1 and c-myc expression, slower proliferation, and repressed transformed phenotype." (PMID 27153093, 2016). "Similarly, in ER- breast cancer cells RelB has been shown to be constitutively active since ER is known to inhibit RelB expression." (PMID 27764181, 2016). "Furthermore, Vogel and colleagues showed that TCDD induced dimerization of AhR and RelB of the alternative NF-κB pathway and up-regulation of CXCL8 through a novel RelB/AhR response element (RelBAHRE) in macrophages and breast cancer cells." (PMID 25201625, 2014). "Given that RelB and p52 have been shown to be activated in other tumour types such as B- and T-cell lymphomas as well as in breast carcinoma, they may also play a role in prostate cancer development and progression." (PMID 16205698, 2005). "In addition, RelB signaling pathway promoted senescence-like growth arrest in breast cancer." (PMID 37388242, 2023). "Using samples from breast cancer patients, we found that AhR is frequently over-expressed in ER-negative human breast tumors, and this is closely correlated with elevated expression of the NF-кB subunit RelB and inflammatory markers such as IL-8 (CXCL1 in mouse) and COX-2." (PMID 36588678, 2022).
breast carcinoma (continued). "We have uncovered a previously unknown signaling pathway implicating p21-activated kinase 4 (PAK4) in the control of senescence in breast cancer, via the nuclear factor kappa-light-chain-enhancer of activated B cells (NF-κB) subunit RELB and the CCAAT-enhancer-binding protein beta (C/EBPβ)." (PMID 32158912, 2020). "Additionally, inhibition of RelB with vitamin D3 sensitized breast cancers to ionizing radiation." (PMID 27764181, 2016). "A published report has shown that the NF-κB member, RelB, plays a role in upregulating GPX4 expression and suppressing ferroptosis, thereby increasing the resistance of ER+ breast cancer cells to Tamoxifen." (PMID 39833180, 2025). "We determined the effect of NF-κB activation in DAB2IP-low Luminal A breast cancer by profiling RELA, RELB, and NFKB2 genomic binding and gene expression using ChIP-Seq in stable DAB2IP knockdown and control T47D cells." (PMID 39418101, 2024). "BRD4 degrader reduced BRD4, PD-L1, RelB, and IL-6 levels and overexpression of PD-L1 of ARV-825 treated breast cancers increased reduced PD-L1, RelB, and IL-6 levels." (PMID 37924094, 2023). "RelA and RelB are able to decrease the levels of MCAM and CD146 adhesion molecules in the release of EVs, leading to breast cancer metastasis." (PMID 35765040, 2022). "Comparison of human mammary epithelial cells (HMECs) to mesenchymal claudin-low SUM159 breast cancer cells revealed decreases in REL transcript and increases in RELB transcript in SUM159s relative to HMECs." (PMID 32859943, 2020). "We recently reported that in aggressive ER- breast cancer, EZH2 complexes with RelA/RelB and binds to the Notch1 promoter to activate transcription independent of its methyltransferase activity." (PMID 30022044, 2018). "Previously it was shown that RelB and EZH2 are important for the self-renewal of breast cancer TICs." (PMID 27764181, 2016). "RELA, RELB, CREL, NFKB1 and NFKB2, and the upstream regulators NEMO and NIK were knocked-down in lymph endothelial cells (LECs) and in MDA-MB231 breast cancer spheroids to study the contribution of NF-κB in vascular barrier breaching." (PMID 26513020, 2015). "Overexpression of RelA in a breast cancer cell line or pro-B cells, and expressing cRel in HELA cells and RelB in murine fibroblasts retards proliferation." (PMID 26460486, 2015). "Along this line, RelB (non-canonical NF-κB activation) overexpression in breast cancer cells induced cathepsin D downregulation." (PMID 36612268, 2022). "RELB is found to be expressed at higher levels in Breast cancer in regulating the noncanonical NF-κB pathway." (PMID 36452073, 2022). "We used the STRING bioinformatic tool to find biological processes associated with the gene products that we analyzed for their prognostic impact on breast cancer, namely IKKα (CHUK), IKBKB, p50/NFKB1, p65/RELA, NIK (MAP4K4), p52 (NFKB2), RELB, IL-8 (CXCL8), IL6, and MMP-1." (PMID 31602271, 2019). "It is, therefore, intriguing that activity of the noncanonical NF-κB transcription factors RelB and p100/p52 (NFKB2) have been implicated in promoting breast cancer." (PMID 29874793, 2018). "Higher RelB expression has been demonstrated in oestrogen receptor α (ERα)-negative breast cancers, due in part to repression of RelB synthesis by ERα signalling." (PMID 29983639, 2018). "However, since the critical upstream kinase NIK, has not been found to be widely stabilized in breast cancer cells, more work needs to be done to uncover the mechanisms by which RelB and NFKB2 expression and activity are promoted in breast cancers." (PMID 29874793, 2018). "It has been recently reported that RelB can promote the more invasive phenotype of ERα-negative breast cancer cell lines, and RelB increases the incidence of metastatic tumors in a mice xenograft model of prostate cancer." (PMID 27153093, 2016).
breast carcinoma (continued). "In order to determine if these effects are unique to the triple negative subtype of breast cancer, the contribution of RelB and EZH2 to the self-renewal capacity of several ER+ cell lines was tested." (PMID 27764181, 2016). "Noncanonical NF-κB activation, which leads to RelB activation, has also been reported in breast carcinoma, prostate cancer, and lymphoid leukemia." (PMID 18596915, 2008). "Interestingly, AhR as well as NFkB RelB have been shown to induce IDO expression, which is also critically involved in the immunosuppressive mechanisms of myeloid-derived suppressor cells (MDSCs) in breast cancer." (PMID 36588678, 2022). "Although some genes, such as DHX34 and RELB, have not yet been shown to be directly related to breast cancer, it’s possible that they could lead to the discovery of new breast cancer related genes or biomarkers." (PMID 33371906, 2020). "Thus, PAK4 is a negative regulator of NF-κB signaling in breast cancer cells, regulating senescence-like growth arrest via the noncanonical NF-κB subunit RELB." (PMID 31399573, 2019). "Here we identify PAK4 as an attractive breast cancer drug target candidate given its overexpression in breast cancer patients negatively affecting prognosis and its key function in evading senescence-like growth arrest in breast cancer cells via the noncanonical NF-κB component RELB." (PMID 31399573, 2019). "We identify PAK4 as an inhibitor of NF-κB signaling in breast cancer and show that the senescence-like growth arrest upon PAK4 knockdown in cancer cells functionally requires the noncanonical NF-κB subunit RELB." (PMID 31399573, 2019). "In line with the notion that RELB signaling promotes growth arrest, overexpression of FLAG-tagged RELB wt led to reduced EdU incorporation in Hs 578T breast cancer cells, while expression of a FLAG-tagged phospho-mimicking RELB–S151E (Ser→Glu substitution) did not affect proliferation." (PMID 31399573, 2019).